HSF5 (heat shock transcription factor 5)
Description:
DNA-binding transcription factor that is essential for male fertility, spermatogenesis and meiotic prophase progression in spermatocytes under non-stress conditions. Positvely and negatively regulates gene expression to ensure progression of meiotic prophase beyond pachytene stage in spermatocytes.
Synonyms: HSF 5; HSTF 5; FLJ40311
Tractability: No criterion of Open Targets' tractability assessment is met for any kind of drug.
Gene: Protein-coding gene on chromosome 17 (58,420,167 to 58,488,408, reverse strand). Ensembl gene ENSG00000176160.
Subcellular location: Nucleus; Chromosome
Subcellular location (Human Protein Atlas): Nucleoplasm
Gene Ontology:
Molecular function: sequence-specific double-stranded DNA binding; RNA polymerase II cis-regulatory region sequence-specific DNA binding; DNA-binding transcription activator activity; DNA-binding transcription factor activity; DNA-binding transcription repressor activity; sequence-specific DNA binding
Biological process: regulation of transcription by RNA polymerase II; male meiotic nuclear division; negative regulation of DNA-templated transcription; positive regulation of DNA-templated transcription; regulation of DNA-templated transcription; spermatogenesis
Cellular component: chromosome; nucleus; XY body
Genetic constraint (gnomAD): Loss-of-function variants: 5 observed, 41.15 expected, observed/expected ratio (o/e) 0.12, 90% interval 0.063 to 0.25. The upper end of that interval is the gene's LOEUF score, 0.25, which puts it in group 1 of 6, group 1 being the genes least tolerant of losing a copy. Missense variants: 509 observed, 664.04 expected, observed/expected ratio (o/e) 0.77, 90% interval 0.71 to 0.82. Synonymous variants: 283 observed, 270.05 expected, observed/expected ratio (o/e) 1.05, 90% interval 0.95 to 1.16.
Homologues: Orthologues: chimpanzee HSF5 (99% identical), macaque HSF5 (97% identical), dog HSF5 (91% identical), pig HSF5 (90% identical), guinea pig HSF5 (90% identical), mouse Hsf5 (90% identical), rat Hsf5 (89% identical), rabbit HSF5 (86% identical), Drosophila melanogaster Hsf (11% identical), Caenorhabditis elegans hsf-1 (9% identical). Paralogues in human: HSFX1 (13% identical), HSFX2 (13% identical), HSF1 (13% identical), HSF4 (13% identical), HSF2 (11% identical), HSFY1 (11% identical), HSFY2 (11% identical), HSFX3 (10% identical), HSFX4 (9% identical).
Diseases named in the same sentence as HSF5 in open-access papers:
HSF5 is named in the same sentence as 11 diseases in open-access papers, as found by Europe PMC text mining. Sharing a sentence is not in itself a finding about the gene and the disease. The quoted sentences say what the papers report.
male infertility (6 papers, 2023 to 2026). The inability of the male to effect fertilization of an ovum after a specified period of unprotected intercourse. "The findings identify HSF5 as a novel genetic cause for human male infertility associated with meiotic arrest." (PMID 38958533, 2024). "Here, through the innovative chromatin-associated protein screening method, we identified a novel candidate HSF5, loss of which leads to severe meiotic arrest, abnormal pachynema with accumulated apoptotic spermatocytes, and eventually male infertility." (PMID 39162221, 2024). "Deficiency of HSF5 results in meiotic arrest and male infertility, characterized as unconventional pachynema arrested at the mid-to-late stage, with extensive spermatocyte apoptosis." (PMID 39162221, 2024). "HSF5 is one of the newest members of the family, and although it is expressed in humans, its roles are better understood in animals: in the zebrafish, HSF5 loss of function leads to male infertility, and in mice, HSF5 is known to be involved in spermatogenesis." (PMID 36765939, 2023). "For instance, HSF5 may serve as a diagnostic marker for clinical cases of idiopathic infertility, such as those seen in non-obstructive azoospermia patients, and could provide a foundation for the development of gene-editing therapies for male infertility in the future." (PMID 41567493, 2026). "Hsf5 knockout (Hsf5 KO) mice exhibited impaired pachynema progression, increased spermatocyte apoptosis, and male infertility." (PMID 41567493, 2026). "HSF5 knockout fish display male infertility due to drastically reduced sperm count and defects in sperm morphology, which were attributed to transcriptional dysregulation of cell cycle and apoptosis genes." (PMID 40457168, 2025). "Thus, the later stages of spermatogenesis were abolished in Hsf5 KO seminiferous tubules, resulting in male infertility." (PMID 38684656, 2024). "We further demonstrated that in mice, the loss of HSF5 is associated with abnormal meiotic recombination, synapsis, crossover, and meiotic sex chromosome inactivation (MSCI), leading to meiotic arrest at the late pachytene stage and ultimately male infertility." (PMID 38958533, 2024). "Similar to HSF1 and HSF2 double knockouts, mice lacking HSF5 exhibit stalling of spermatogenesis at the spermatocyte stage, leading to male infertility." (PMID 40457168, 2025). "The absence of HSF5 resulted in a gradual halt in progression from mid- to late pachynema, ultimately leading to spermatocyte apoptosis and male infertility." (PMID 39162221, 2024).
infertile (2 papers, 2024). "Patients with a pathogenic variant of HSF5 are completely infertile." (PMID 38958533, 2024). "To elucidate the etiology of infertility in Hsf5 KO males, we examined the histology of Hsf5 KO testes by H&E staining." (PMID 38958533, 2024). "However, Hsf5−/− males demonstrated infertility and markedly diminished testicular size relative to Hsf5+/+ and Hsf5+/− littermates, with fertility tests confirming the infertility of Hsf5−/− males but the fertility of Hsf5−/− females." (PMID 39162221, 2024). "We thus speculated that this HSF5 homozygous missense mutation leads to a lack of protein expression, which might be responsible for the infertility phenotype of the two siblings." (PMID 38958533, 2024).
prostate adenocarcinoma (2 papers, 2021 to 2023). "HSP90AA1 gene expression was not significantly correlated with the gene expression of HSF1, HSF2, and HSF5 in prostate adenocarcinoma specimens." (PMID 36982267, 2023). "Downregulated HSF5 expression was also observed in various cancers, including bladder urothelial carcinoma (BLCA), colon adenocarcinoma (COAD), kidney chromophobe (KICH), lung squamous cell carcinoma (LUSC), prostate adenocarcinoma (PRAD) and thyroid carcinoma (THCA)." (PMID 33390814, 2021).
Azoospermia (1 paper, 2024). Absence of any measurable level of sperm,whereby spermatozoa cannot be observed even after centrifugation of the semen pellet. "The currently available HSF5 antibody‐targeting ChIP experiments have higher specificity for the human protein than for the mouse protein; thus, we performed ChIP‐seq on human testis samples from obstructive azoospermia patients." (PMID 38958533, 2024).
thyroid cancer (1 paper, 2021). "Moreover, lower HSF5 expression was also observed in bladder, colon, kidney, prostate and thyroid cancers based on TIMER." (PMID 33390814, 2021).
viral infections (1 paper, 2025). "Consequently, a putative role of HSF5, HSFX, and HSFY in viral infections cannot be disregarded." (PMID 40457168, 2025). "To date, no involvement of HSF5, HSFX, or HSFY in viral infections has been reported." (PMID 40457168, 2025).
cancer (2 papers, 2021 to 2025). A tumor composed of atypical neoplastic, often pleomorphic cells that invade other tissues. "The altered expression of HSF5 in cancer was also associated with gene expression changes in the immune response and inflammatory signaling pathways." (PMID 40457168, 2025). "In addition to the extensive involvement of HSF1 in cancer, both HSF2 and HSF4 have been shown to affect cancer cell proliferation and invasion, and altered expression of HSF5 is associated with several cancer types." (PMID 40457168, 2025). "Interestingly, while HSF5 is most prominently expressed in testes, it is reportedly downregulated in several cancer types and correlates with poor patient survival in lung adenocarcinoma." (PMID 40457168, 2025). "HSF5 has not previously been connected to cancer, and in this study, we demonstrated the low expression and prognostic value of HSF5 in LUAD." (PMID 33390814, 2021). "However, the functional characterization of HSF5 involved in cancer and the immune response has not been conducted." (PMID 33390814, 2021).
tumor (2 papers, 2021). "This study revealed the crucial role of HSF5 in LUAD and an underlying mechanism between HSF5 and tumor-immune interactions." (PMID 33390814, 2021). "Importantly, the correlation between HSF5 expression and the marker genes of these immune cells implicates the function of HSF5 in regulating tumor immunology." (PMID 33390814, 2021). "Additionally, we analyzed the differences in HSF5 expression in various tumor and normal tissues." (PMID 33390814, 2021). "Based on the Tumor IMmune Estimation Resource (TIMER) and Gene Expression Profiling Interactive Analysis (GEPIA) datasets, HSF5 expression showed strong correlations with various immune cell infiltration and diverse immune marker sets." (PMID 33390814, 2021).
HSF5 also shares sentences with these, for which no sentence is quoted: bladder urothelial carcinoma (1 paper); colon adenocarcinoma (1); lung squamous cell carcinoma (1).